TRPM7 (transient receptor potential cation channel subfamily M member 7)
Diseases named in the same sentence as TRPM7 in open-access papers (continued):
Sharing a sentence is not in itself a finding about the gene and the disease.
ovarian carcinoma (continued). "Thus, HIF-1α over-expression significantly mitigated or abrogated the TRMP7 silencing-decreased glycolysis and inhibition of AMPK abrogated the TRPM7 silencing-enhanced OXPHOS in ovarian cancer cells." (PMID 35101076, 2022). "These may partially explain why TRPM7 silencing inhibited ovarian cancer cell proliferation and tumor growth." (PMID 35101076, 2022). "Inhibition of TRPM7 can minimize the malignant behaviors of ovarian cancer." (PMID 35101076, 2022). "Hence, TRPM7 acts as an oncogenic factor to promote ovarian cancer growth and is a potential target for development of therapies for ovarian cancer." (PMID 35101076, 2022). "Given that glycolysis inhibition is associated with HIF-1α degradation we hypothesize that TRPM7 activation may modulate the HIF-1α/AMPK signaling to regulate glucose metabolism and promote ovarian cancer cell proliferation." (PMID 35101076, 2022). "Together, our findings indicate that TRPM7 is a novel therapeutic target and may shed new light on the regulation of metabolic reprogramming and pathogenesis of ovarian cancer." (PMID 35101076, 2022). "Furthermore, treatment with CC to inhibit AMPK activation restored HIF-1α protein levels in both control and TRPM7 silencing ovarian cancer cells under hypoxic and normoxic conditions." (PMID 35101076, 2022). "Moreover, treatment with CC also decreased the ubiquitination of HIF-1α in both control and TRPM7 silencing ovarian cancer cells under hypoxic and normoxic conditions." (PMID 35101076, 2022). "However, little is known on how transient receptor potential 7 (TRPM7) modulates metabolic reprogramming in ovarian cancer." (PMID 35101076, 2022). "Our results indicated that TRPM7 silencing shifted glycolysis to OXPHOS in ovarian cancer cells." (PMID 35101076, 2022). "The same group proposes TRPM7 as a modulator of metabolic reprogramming pathways in ovarian cancer." (PMID 36844925, 2022). "Accordingly, we speculate that TRPM7 silencing may suppress the proliferation of ovarian cancer cells by shifting metabolic reprogramming." (PMID 35101076, 2022). "Conceivably, these findings may uncover the regulation of the TRPM7/AMPK/HIF-1α axis on the glucose metabolic reprogramming in ovarian cancer." (PMID 35101076, 2022). "Moreover, TRPM7 silencing in ovarian cancer cell lines SKOV3 and OVCAR3 reduced EGF-dependent migration, invasion and wound healing." (PMID 34360952, 2021). "Additionally, TRPM7 upregulation was positively correlated with lymph node involvement and poor prognosis in patients with ovarian cancer." (PMID 34938330, 2021). "Furthermore, a more recent study described a role for TRPM7 in EMT induction via PI3K signaling in ovarian cancer cells." (PMID 34936030, 2021). "Furthermore, a research using ovarian cancer confirmed TRPM7 silencing reduces the EMT process, which eventually reduces migration, invasion, and wound healing of cancer cells." (PMID 32168794, 2020). "Our previous studies have suggested that TRPM7 may be a prognostic factor for patients with ovarian cancer." (PMID 30819230, 2019). "Accordingly, we hypothesize that TRPM7 may regulate the EMT process of ovarian cancer cells by regulating the levels of [Ca2+]i to activate the PI3K/AKT signaling, leading to invasion and metastasis of ovarian cancer." (PMID 30819230, 2019). "Moreover, treatment with BAPTA-AM mitigated the IGF-stimulated migration, invasion, particularly in TRPM7-silenced ovarian cancer cells." (PMID 30819230, 2019). "Given that the high levels of EMT process are associated with metastasis our findings suggest that up-regulated TRPM7 expression may a valuable factor to predict the metastasis of ovarian cancer." (PMID 30819230, 2019). "Our previous study has revealed that up-regulated TRPM7 expression is related to pelvic lymph node metastasis and poor prognosis of human ovarian cancer and inhibition of TRPM7 can suppress the invasion and metastasis of ovarian cancer cells through attenuating the Ca2+-PI3K/AKT signaling." (PMID 35101076, 2022).
ovarian carcinoma (continued). "Hence, our findings may uncover the new function of TRPM7 in the growth of ovarian cancer and imply that TRPM7 may be a new target for design of therapies for ovarian cancer." (PMID 35101076, 2022). "Finally, we tested whether TRPM7 silencing-decreased EMT process could be attributed to decreased levels of calcium-related PI3K/AKT signaling in ovarian cancer cells." (PMID 30819230, 2019). "Our findings suggest that TRPM7 may be a therapeutic target for intervention of ovarian cancer." (PMID 30819230, 2019). "Hence, TRPM7 may be new therapeutic target for prevention and intervention of ovarian cancer metastasis." (PMID 30819230, 2019). "Our previous study has shown that TRPM7 is highly expressed in ovarian cancer tissues and cells, especially in metastatic ovarian cancer tissues, and the expression levels are positively correlated with pelvic lymph node metastasis and poor prognosis in ovarian cancer patients." (PMID 30819230, 2019). "Thus, TRPM7 levels may be valuable for the prognosis of metastasis and TRPM7 may be a therapeutic target for prevention and intervention of metastasis of ovarian cancer." (PMID 30819230, 2019). "Hence, TRPM7 silencing reduced the levels of [Ca2+]i in ovarian cancer cells." (PMID 30819230, 2019). "The Subsequently, we investigated how the silencing of TRPM7 affected AMPK activation, the expression of HIF-1α, OXPHOS, and glycolysis in ovarian cancer cells." (PMID 40813985, 2025). "To understand how TRPM7 silencing modulates the HIF-1α and AMPK signaling, we characterized the levels of HIF-1α and AMPK expression and activation in the indicated ovarian cancer cells by Western blot and IHC." (PMID 35101076, 2022). "While TRPM7 silencing significantly increased the production of ATP, ROS and the ratios of NAD+/NADPH as well as OCR in ovarian cancer cells, which were significantly mitigated or abrogated by treatment with CC." (PMID 35101076, 2022). "Mechanistically, TRPM7 silencing significantly increased AMPK phosphorylation and decreased HIF-1α protein levels in ovarian cancer, particularly in HIF-1α silencing cells." (PMID 35101076, 2022). "Mechanistically, TRPM7 silencing enhanced AMPK activation and promoted HIF-1α ubiquitination and degradation in ovarian cancer cells." (PMID 35101076, 2022). "Together, TRPM7 silencing enhances the AMPK activation and decreases HIF-1α protein levels to shift glycolysis to OXPHOS in ovarian cancer cells." (PMID 35101076, 2022). "Hence, TRPM7 may be a therapeutic target for intervention of ovarian cancer." (PMID 35101076, 2022). "More importantly, we found that TRPM7 silencing promoted HIF-1α ubiquitination and degradation in ovarian cancer cells." (PMID 35101076, 2022). "In ovarian cancer SKOV3 and OVCAR3 cell lines, TRPM7 depletion inhibited migration and invasion, and decreased metastasis to the lung in SKOV3 tumors, therefore prolonging the survival of mice with this type of tumors." (PMID 36844925, 2022). "Collectively, these results indicate that TRPM7 silencing shifts glycolysis to OXPHOS in ovarian cancer, inhibiting ovarian cancer growth." (PMID 35101076, 2022). "Our data indicated that TRPM7 silencing shifted glycolysis to OXPHOS in ovarian cancer cells and attenuated ovarian cancer cell proliferation and tumor growth." (PMID 35101076, 2022). "Our data revealed that TRPM7 silencing down-regulated HIF-1α expression, but enhanced AMPK activation in ovarian cancer cells, extending previous observations." (PMID 35101076, 2022). "We found that TRPM7 silencing enhanced OXPHOX, inhibited glucose uptake, glycolysis, lactic acid production and suppressed the proliferation of ovarian cancer cells by enhancing AMPK activation and HIF-1α degradation." (PMID 35101076, 2022). "Next, we explored how TRPM7 silencing modulated AMPK activation, HIF-1α expression, OXPHOS and glycolysis in ovarian cancer cells." (PMID 35101076, 2022).
ovarian carcinoma (continued). "In parallel, TRPM7 silencing decreased the glucose uptake of tumor-bearing mice and TRPM7 levels were negatively correlated with IDH3B and UQCRC1, but positively with HK2 and PDK1 expression in ovarian cancer tissues." (PMID 35101076, 2022). "The shifting from glycolysis to OXPHOS by TRPM7 silencing was abrogated by HIF-1α over-expression and impaired by inhibiting AMPK activity in ovarian cancer cells." (PMID 35101076, 2022). "Evidently, TRPM7 silencing significantly minimized glucose uptake, lactic acid production, ECAR, but elevated ATP and ROS levels, NAD+/NADH ratios and OCR in ovarian cancer cells." (PMID 35101076, 2022). "According to their results, TRPM7 suppression inhibits EMT process and ovarian cancer metastasis through reducing calcium-related PI3K/AKT activation." (PMID 34938330, 2021). "Suppression of TRPM7 was determined to inhibit migration and invasion in SKOV3 and OVCAR3 cells, which are well-known ovarian cancer cell lines." (PMID 34938330, 2021). "In this study, we found that up-regulating TRPM7 expression was correlated with increased EMT process in ovarian cancer tissues and with poor disease-free and overall survival of ovarian cancer patients in this population." (PMID 30819230, 2019). "TRPM7 silencing enhanced the EMT and F-actin expression and mitigated the EGF-enhanced EMT process in ovarian cancer cells." (PMID 30819230, 2019). "TRPM7 silencing inhibited the EMT and metastasis of ovarian cancer by attenuating the calcium-related PI3k/AKT activation." (PMID 30819230, 2019). "(C, D) Inhibition of TRPM7 expression by MK886 mitigated the EGF-induced migration, invasion and wound healing of ovarian cancer cells." (PMID 30819230, 2019). "The expression of TRPM7 and EMT markers (Vimentin, N-cadherin, Twist and E-cadherin) in ovarian cancer samples was detected." (PMID 30819230, 2019). "It has been showed that silencing TRPM7 may activate AMPK, which aids the degradation of HIF-1α ubiquitinated proteasome in ovarian cancer." (PMID 39633507, 2024). "In vitro and in vivo, silencing TRPM7 increased the activation of AMPK and stimulated the ubiquitination and degradation of HIF-1α, thus attenuating the HIF-1α-enhanced glycolysis, and inhibiting the proliferation of ovarian cancer cells." (PMID 36844925, 2022). "The impacts of TRPM7 silencing on the levels of glycolysis-related HK2, PDK1 and oxidative phosphorylation (OXPHOS)-related IDH3B and UQCRC1, HIF-1α expression and AMPK phosphorylation were determined in ovarian cancer." (PMID 35101076, 2022). "Hence, TRPM7 silencing modulated the levels of glycolysis- and OXPHOS-related enzyme expression to shift glycolysis to OXPHOS in ovarian cancer." (PMID 35101076, 2022). "Therefore, TRPM7 silencing enhanced AMPK activation to promote the ubiquitination and proteasomal degradation of HIF-1α, shifting glycolysis to OXPHOX in ovarian cancer cells." (PMID 35101076, 2022). "In ovarian cancer, TRPM7 expression was significantly increased compared to non-tumor tissues, and was negatively correlated with E-cadherin and positively correlated with mesenchymal markers vimentin and Twist." (PMID 34360952, 2021). "Moreover, TRPM7 suppression was seen to reduce lung metastasis of SKOV3 tumor cells and extended survival of mice with ovarian cancer." (PMID 34938330, 2021). "Thus, TRPM7 silencing inhibited the EMT process, contributing to its metastatic inhibition in ovarian cancer." (PMID 30819230, 2019). "Thus, TRPM7 silencing decreased the calcium signaling and inhibited the PI3K/AKT activation to attenuate the EMT process, impairing migration and invasion of ovarian cancer cells." (PMID 30819230, 2019). "Western blot analysis revealed a similar pattern of TRPM7, E-cadherin, Vimentin and Twist expression in some ovarian cancer and non-tumor tissues." (PMID 30819230, 2019). "Finally, TRPM7 silencing attenuated the PI3K/AKT activation, which was enhanced by BAPTA-AM, MK886 or LY2904002 treatment in ovarian cancer cells." (PMID 30819230, 2019).
ovarian carcinoma (continued). "In this study, we found that TRPM7 silencing by specific shRNA significantly decreased the levels of TRPM7 expression and attenuated the EGF-induced migration, invasion and wound healing of ovarian cancer cells in vitro." (PMID 30819230, 2019). "Furthermore, inhibition of TRPM7 expression by MK886 also significantly attenuated the EGF-induced migration, invasion and wound healing of ovarian cancer cells by inhibiting the EMT process." (PMID 30819230, 2019). "TRPM7 silencing, inhibition of TRPM7 expression or inhibition of the calcium channel decreased the levels of [Ca2+]I and attenuated the EMT process, migration, invasion and wound healing of ovarian cancer cells by inhibiting the PI3K/AKT activation." (PMID 30819230, 2019). "The effects of TRPM7 silencing on transcriptome profile, glucose uptake, lactic acid production, extracellular acidification rate (ECAR), oxygen consumption rate (OCR), intracellular ROS and ATP levels, and NAD+/NADH ratios in ovarian cancer cells were examined." (PMID 35101076, 2022). "It is possible that TRPM7 silencing may activate the AMPK to promote HIF-1α ubiquitination proteasomal degradation that attenuates the HIF-1α-enhanced glycolysis to shift glycolysis to OXPHOS, inhibiting the proliferation of ovarian cancer cells." (PMID 35101076, 2022). "Furthermore, TRPM7 silencing also decreased the relative levels of glycolysis-related HK2 and PDK1 expression as well as PKM2 nuclear translocation, but increased OXPHOS-related IDH3B and UQCRC1 expression in ovarian cancer cells and tissues." (PMID 35101076, 2022). "Treatment with MG132, a proteasome inhibitor, remarkably restored HIF-1α protein levels in ovarian cancer cells regardless of hypoxia condition and TRPM7 silencing, indicating that TRPM7 silencing promoted the ubiquitination and proteasomal degradation of HIF-1α." (PMID 35101076, 2022). "Finally, similar patterns of TRPM7, E-cadherin, Vimentin and Twist expression were observed in ovarian cancer cells and non-tumor ovarian epithelial cells." (PMID 30819230, 2019).
atrial fibrillation (19 papers, 2010 to 2023). A disorder characterized by an electrocardiographic finding of a supraventricular arrhythmia characterized by the replacement of consistent P waves by rapid oscillations or fibrillatory waves that vary in size, shape and timing and are accompanied by an irregular ventricular response. "In the cardiovascular system, TRPM7 has been implicated in atrial fibrillation, cardiac remodeling, vascular smooth muscle phenotypic switching, vascular calcification." (PMID 36878949, 2023). "Here we report that impaired channel function of TRPM7 in MKs causes macrothrombocytopenia in mice (Trpm7fl/fl-Pf4Cre) and likely in several members of a human pedigree that, in addition, suffer from atrial fibrillation." (PMID 27020697, 2016). "Significant increases in these Ca2+ influxes from p.R494Q TRPM7 in the developing atrial myocardium could predispose developing fetal hearts to atrial fibrillation." (PMID 31423533, 2020). "Although TRPM6 expression was found to be upregulated in the right atria of atrial fibrillation patients in comparison with sinus rhythm patients, the endogenous currents recorded in human atrial fibroblasts are encoded by TRPM7, as TRPM7 siRNA eliminates the majority of TRPM7-like currents." (PMID 31547577, 2019). "Additionally, TRPM7 is implicated in atria with atrial fibrillation or membrane rupture, ischemia reperfusion in transplanted kidney, and hyperglycemia-induced injury in vascular endothelia." (PMID 25079291, 2014). "A very recent study in atrial fibroblasts observed TRPM7 channels that account for Ca2+ influx in atrial fibroblasts and are markedly upregulated in patients with atrial fibrillation where they may underlie pathological fibrosis." (PMID 21203483, 2010). "Abnormal TRPM7 activity has been implicated in hypertension, cardiac fibrosis, inflammation and atrial fibrillation (AF), with TRPM7 downregulation promoting cardiovascular injury." (PMID 36818331, 2023). "- Membrane tension activates TRPM7 channels and Ca2+ flickers, directing migration in human embryonic lung fibroblasts. - Transforming growth factor-β increased expression of TRPM7 in human atrial fibroblasts associated with myofibroblast differentiation and fibrogenesis in atrial fibrillation." (PMID 25079291, 2014). "In the last decade, increasing evidence have established a link between TRPM7 and atrial fibrillation (AF), which is most commonly sustained arrhythmia and a major cause of morbidity and mortality." (PMID 36818331, 2023). "TRPM7 is markedly upregulated in atrial fibrillation (AF) patients, activating the calcineurin pathway and producing a synergistic effect with TGFβ1, and resulting in the activation of fibroblasts." (PMID 35359592, 2022). "In human atrial fibrillation, Ca2+ entry through TRPM7 channel plays a pivotal role in TGF-β1-elicited fibrogenesis in atrial fibroblasts." (PMID 34778271, 2021). "TRPM7 is the major Ca2+ channel in atrial fibroblasts, and up-regulation of these transients is reported in patients with atrial fibrillation." (PMID 31423533, 2020). "TRPM7 is up-regulated by 3- to fivefold in CFs from patients with atrial fibrillation compared with sinus rhythm patients." (PMID 30523498, 2019). "Variability of the TRPM7 current density in human cardiomyocytes is related to the clinical history, being higher in atrial fibrillation and in ischemic cardiomyopathy." (PMID 28129376, 2017). "- TRPM7-like current was recorded in human atrial myocytes, and expression of TRPM7 is up-regulated in atria with atrial fibrillation or membrane rupture." (PMID 25079291, 2014). "No significant change was observed in TRPM4 protein, while remarkable increase was observed in TRPM7 protein in the three atrial samples from patients with atrial fibrillation." (PMID 22802050, 2012). "The density of Mgi2+-sensentive TRPM7 current was greater in myocytes with atrial fibrillation than that in cells with sinus rhythm." (PMID 22802050, 2012).